TNF (tumor necrosis factor)
Diseases named in the same sentence as TNF in open-access papers (continued):
Sharing a sentence is not in itself a finding about the gene and the disease.
Obesity (continued). "Obesity drives chronic low-grade systemic inflammation, characterized by elevated levels of pro-inflammatory cytokines, including tumor necrosis factor alpha (TNF-α), interleukin (IL)-6, and C-reactive protein (CRP)." (PMID 40703374, 2025). "Newborns from mothers with overweight and obesity have a higher expression of inflammation genes, TNF‐α, nuclear factor kappa‐light‐chain‐enhancer of activated B cells (NFkB) and Toll‐like receptor 4 (TLR4), in the cord‐blood than newborns from women with normal weight." (PMID 41452351, 2025). "This may be due to the pro-inflammatory nature of obesity, with over-expression of IL-6, TNF-alpha, and adipokines in visceral and mesenteric fat." (PMID 40156753, 2025). "Evidence synthesis across multiple RCTs shows that semaglutide reduces hsCRP by 12–20%, TNF-α by 15–40%, and IL-6 by 10–25%, independent of weight loss or glycemic effects, in patients with type 2 diabetes and obesity." (PMID 41511355, 2025). "Circulating TNF‐α levels are elevated in individuals with obesity and T2DM and correlate positively with measures of insulin resistance, such as the homeostasis model assessment of insulin resistance (HOMA‐IR), further implicating TNF‐α–driven inflammation in the pathogenesis of metabolic disease." (PMID 41268160, 2025). "At the same time, adipocytes in the adipose tissue of patients with obesity can synthesize high levels of proinflammation cytokines, including TNF-α, LI-6, and IL-1β, which may induce systemic inflammation after entering the blood." (PMID 39722113, 2025). "Serum Wnt5a, leptin, and TNF-α levels increase in women with obesity and the A allele of TLR2 (Arg753Gln) SNP could be protective against obesity-associated metaflammation." (PMID 39837875, 2025). "Obesity promotes a pro-inflammatory environment by elevating the levels of inflammatory mediators such as IL-6 (interleukin) and tumor necrosis factor alpha (TNF-α), while decreasing adiponectin, a molecule that has anti-inflammatory properties." (PMID 40943267, 2025). "Elevated TNF‐α levels in obesity downregulate eNOS mRNA stability." (PMID 41387361, 2025). "Obesity fosters a state of chronic low-grade inflammation through adipose tissue dysfunction, characterized by the excessive secretion of pro-inflammatory cytokines such as IL-6, TNF-α, and IL-1β." (PMID 40004007, 2025). "Thus, this suggests that in vitro treatment with TNFα in our study mimics the pathophysiology of obesity-related mitochondrial dysfunction." (PMID 39269560, 2025). "Furthermore, obesity exacerbates the pathological effects of VC, a condition that significantly increases levels of ASAs and pro-inflammatory cytokines such as IL-1 and TNF-α." (PMID 40564033, 2025). "Obesity-induced inflammation tends to exacerbate metabolic disorders, and we also found improvements in inflammatory markers, manifested as the decrease of inflammatory factors TNF-α, IL-1α, IL-6, and chemokine Eotaxin elicited by nicotine." (PMID 41488304, 2025). "In this respect, the increased secretion of IL-6 and TNF-α in chronic inflammation-related obesity may activate the HPA axis and promote depressive behaviour." (PMID 41375608, 2025). "Although obesity is typically linked to elevated TNF-α, our negative BMI–TNF-α association likely reflects compensatory anti-inflammatory adaptations in chronically inflamed adipose tissue." (PMID 40559392, 2025). "Obesity-related asthma is associated with a Th1 immune response (involving TNF-α, IFN-γ, IL-6, and IL-8) rather than a Th2 response (which involved IL-4, IL-5, IL-10, and IL-13)." (PMID 40083433, 2025). "Moreover, the secretion of TNF-α, a key mediator of obesity-induced inflammation and colon cancer development, is an important biomarker of risk of cancer development." (PMID 40136652, 2025). "However, obesity‐driven overproduction of pro‐inflammatory cytokines, such as TNF‐α and IL‐6, suppresses ADPN, further amplifying inflammation and metabolic dysregulation." (PMID 40452002, 2025).
Obesity (continued). "In general, obesity is associated with elevated levels of cytokines originating from both Th2 and Th1 immune responses, including interleukin (IL)-5, IL-10, IL-12, IL-13, Interferon-gamma (IFN-γ), and tumor necrosis factor alpha (TNF-α)." (PMID 41007770, 2025). "In individuals with obesity, inflammation-induced insulin resistance is mediated by immune cells, particularly macrophages, which exhibit increased secretion of interleukins, such as IL-1 and IL-6, as well as tumor necrosis factor (TNF)-α." (PMID 40867585, 2025). "Adipose tissue, especially in the context of obesity, acts as an immunologically active organ, releasing pro-inflammatory cytokines such as TNF-α, IL-6, and IL-1β, which impair insulin signaling, promote endothelial dysfunction, and contribute to vascular inflammation." (PMID 40870891, 2025). "After high fat feeding in cases of obesity, the expression of TNF‐α in adipose tissue increases." (PMID 39764565, 2025). "In addition, our team has studied the inflammation in taste bud cells and demonstrated that diet-induced obesity or LPS-triggered inflammation increased TNF-α, IL-1β, and IL-6 expression, both at mRNA and protein levels, in taste bud cells." (PMID 40284173, 2025). "Obesity may exacerbate systemic inflammation through increased production of adipokines and pro-inflammatory cytokines, such as TNF-α and IL-6, which have been suggested to play a role in the pathogenesis of either PsA or FM." (PMID 40572738, 2025). "However, PARK2 showed broader and stronger associations with obesity-related factors, including BMI, lipid peroxidation (MDA), mitochondrial enzyme release (SDH), and inflammatory markers (TNF-α)." (PMID 41334630, 2025). "However, more studies are necessary to determine the impact of different training variables (i.e., intensity and volume), as well as the combination of exercise with nutritional strategies, on modulating TNF-α in patients with obesity." (PMID 41141350, 2025). "This suggests that TNFα treatment can be used as a basic in vitro model for studying the pathophysiology of mitochondrial dysfunction and related metabolic complications and screening potential anti-obesity therapeutics in 3T3-L1 adipocytes." (PMID 39269560, 2025). "ENOblock inhibited the pathology of diet-induced obesity by acting as a transcriptional repressor of master regulators of lipid homeostasis (Srebp-1a and Srebp-1c), gluconeogenesis (Pck-1), and inflammation (TNF-α and IL-6)." (PMID 40943261, 2025). "This interplay is recognized as a key driver of metaflammation, as ATMs actively contribute to systemic low-grade inflammation in obesity through the secretion of pro-inflammatory cytokines such as TNF-α, IL-6, and IL-1β, which are major instigators of the insulin resistance phenomenon." (PMID 41226484, 2025). "In obesity, pro-inflammatory M1 macrophages infiltrate adipose tissue, and in conjunction with hypertrophic adipocytes, they secrete cytokines such as tumour necrosis factor-alpha (TNF-α), interleukin-6 (IL-6), and monocyte chemoattractant protein-1 (MCP-1)." (PMID 41010046, 2025). "In obesity, particularly with increased visceral fat, adipocytes secrete higher levels of pro-inflammatory cytokines such as interleukin-6 (IL-6) and tumor necrosis factor-alpha (TNF-α), while reducing the secretion of the anti-inflammatory adipokine adiponectin, thereby promoting inflammation." (PMID 41426805, 2025). "In obesity, hypertrophied adipocytes lead to a chronic inflammatory state in adipose tissue, characterized by the infiltration of immune cells and the release of pro-inflammatory mediators, such as IL-6 and TNF-α, contributing to systemic inflammation." (PMID 41020888, 2025). "Moreover, we conducted anti-TNFα therapy and evaluated intestinal permeability and pancreatic inflammation in experimental obesity-related SAP." (PMID 39856555, 2025).
Obesity (continued). "For example, in obesity, specific inflammatory factors such as interferon-γ, tumor necrosis factor (TNF), leptin, insulin, and palmitate activate the mTORC1 pathway, enhancing macrophage glycolysis activity, thereby increasing PD-1 surface expression and suppressing T cell activity." (PMID 40055311, 2025). "Furthermore, key regulators such as TNF-α are secreted by adipocytes and immune cells, which can lead to chronic inflammation and impaired lipid metabolism, leading to obesity-related complications." (PMID 40871683, 2025). "Obesity is characterized by an expansion of adipose tissue that becomes infiltrated by immune cells, notably macrophages, which secrete proinflammatory cytokines such as tumor necrosis factor-α (TNF-α) and interleukin-6 (IL-6)." (PMID 40868103, 2025). "Adipose tissue, particularly in the context of obesity, undergoes pathological expansion characterized by adipocyte hypertrophy, hypoxia, and stress responses that trigger the production of pro-inflammatory cytokines including TNF-α, IL-6, and IL-1β." (PMID 40551741, 2025). "The relationship between obesity and insulin resistance is driven by adipose tissue inflammation, which stimulates cytokine and chemokine release [including interleukin 6 (IL-6), tumor necrosis factor-alpha (TNF-α), and chemokine (C-C motif) ligand 2 (CCL2)] and macrophage recruitment." (PMID 39928502, 2025). "Obesity is commonly considered a condition characterized bylow-grade chronic inflammation, in which macrophages in adipose tissue,especially in abdominal fat, are activated and release pro-inflammatory markerssuch as TNF-α, interleukin-6 (IL-6), and CRP." (PMID 40926826, 2025). "This study also claimed that reducing Eiger/TNFα expression could be used for obesity, type 2 diabetes, and other metabolic syndrome models." (PMID 40024983, 2025). "The impact of obesity as a comorbid condition in RA has been more extensively analyzed in the treatment with TNF inhibitors (TNFi), and there are currently numerous studies in which a higher BMI implies a worse response to bDMARDs, regardless of the route of administration." (PMID 40077690, 2025). "Our results suggest that crude extract of OFI cladodes effectively counteracts the proinflammatory activation of fat cells induced by cell exposure to TNF‐α, a cytokine long known to play a role in glycemic control and insulin resistance in obesity, but which also responds to dietary intervention." (PMID 40377300, 2025). "In detail, it is proved that in obesity, chronic low-grade inflammation is present since adipose tissue produces pro-inflammatory cytokines (e.g., TNF-α, IL-6), chemokines (monocyte chemoattractant protein (MCP1/CCL2), and pro-inflammatory fatty acids, leading to systemic inflammation." (PMID 40566087, 2025). "Similarly, plasma levels of IL-6 and TNF-α are increased in obesity and other pathological conditions, with high levels of these cytokines associated with a greater risk of CVDs." (PMID 40642747, 2025). "In addition, elevation in inflammatory biomarkers via Tumour necrosis factor-α (TNF-α) and Interleukins (ILs) also critically regulates the development of obesity-induced nephropathy." (PMID 40703753, 2025). "However, adiponectin serum levels decrease in obesity due to adiponectin transcription and translation suppression in an adipocyte cell line by TNF, IL-6, and other pro-inflammatory mediators." (PMID 41227271, 2025). "Notably, IL-1β, IL-6, and TNF-α are major proinflammatory cytokines known to be involved in obesity-induced inflammation." (PMID 40118456, 2025). "At the molecular level, obesity is characterized by excessive release of free fatty acids, which promotes lipotoxicity, oxidative stress, and the activation of pro-inflammatory cytokines such as TNF-α and IL-6, contributing to insulin resistance." (PMID 41011571, 2025).
Obesity (continued). "Additionally, HIIT has been found to regulate the levels of certain serum inflammatory markers (TNF-α, IL-10, neutrophil-to-lymphocyte ratio, neutrophil-to-monocyte ratio) in older adults with various conditions such as heart failure, obesity, and sarcopenia." (PMID 40413509, 2025). "Muscle-derived IL-6 can inhibit the production of inflammatory cytokines such as TNF-α and IL-1β, while promoting secretion of anti-inflammatory cytokines like interleukin-10 (IL-10), thereby improving inflammatory profile in patients with sarcopenic obesity." (PMID 41141350, 2025). "Bacterial LPS-induced inflammation may induce TNFRSF12A expression via TNFα signaling; thus, the observed Tnfrsf12 overexpression may be induced by an extracellular stimulus, e.g., LPS derived from obesity-related gut bacterial species." (PMID 40497936, 2025). "Additionally, immunosuppressive therapy (e.g., TNF-α administered for longer than 120 days), obesity in men, low levels of vitamin D, and Parkinson’s disease are considered potential risk factors for melanoma development." (PMID 40136652, 2025). "In the context of obesity, chronic inflammation serves to exacerbate the dysfunction of adipocytes via the activation of NF-κB, which in turn induces the production of pro-inflammatory cytokines (e.g., TNF-α)." (PMID 40002389, 2025). "The possible reason might be, sedentary life style of Ethiopian population leads to obesity and, in obese individual there is an excess formation of aromatase enzyme, leptin hormone and cytokines (TNFα and IL-1β)." (PMID 40811476, 2025). "Other studies confirm the protective effect of education and income on the prevalence of depression and suggest that cytokines like IL-1β, TNFα, or the NF-κB pathway, which play a role in both obesity and depression, could explain the link." (PMID 40284257, 2025). "Additionally, chronic inflammation associated with obesity triggers NOX activation by releasing pro-inflammatory cytokines (e.g., TNF-α, IL-6), which stimulate redox-sensitive signalling pathways." (PMID 40722947, 2025). "Additionally, obesity induces an increased expression of inflammatory cytokines, such as IL-6 and TNF-α, to promote insulin resistance and metabolic dysfunction." (PMID 40863244, 2025). "Moreover, chemerin levels in newly diagnosed hypertensive patients were significantly higher than in normotensive controls and positively correlated with inflammatory markers (hs-CRP, TNF-α, and IL-6), obesity parameters, plasma TGs, and HOMA-IR index." (PMID 40564199, 2025). "In addition to its anti-adipogenic effects, ASA also reduces the obesity-induced expression of inflammatory cytokines (IL-6, TNFα, and MCP-1) and adhesion molecules (ICAM-I and VCAM-I) while enhancing insulin sensitivity in high-fat diet-induced obese mice." (PMID 39859567, 2025). "This phenomenon may represent a mechanism by which obesity‐induced high TNF‐α exposure contributes to the progression of thyroid tumors." (PMID 40620232, 2025). "In inflammatory states—such as obesity, insulin resistance, and type 2 diabetes—the presence of pro-inflammatory cytokines (including interleukins and TNF-α) disrupts the normal functioning of the glycocalyx and the production of nitric oxide (NO), prostacyclin, and endothelin." (PMID 40283140, 2025). "In obesity, an imbalance in adipokine production results in elevated pro-inflammatory mediators (e.g., tumor necrosis factor alpha (TNF-α) and interleukin-6 (IL-6)) and decreased cardioprotective adipokines, such as adiponectin, fostering systemic inflammation and apoptosis." (PMID 40688840, 2025). "This may be attributed to the increased release of pro-inflammatory factors such as TNF-α and IL-6 in patients with higher levels of obesity, which inhibit nerve regeneration and lead to slower postoperative recovery of neural signal conduction." (PMID 40491428, 2025). "IL6 and TNFα are found in high levels of obesity and activate the PI3K/Akt pathway." (PMID 40040878, 2025).
Obesity (continued). "Obesity may diminish the effectiveness of systemic therapies, including biologic agents such as TNF-α inhibitors." (PMID 40277935, 2025). "In terms of inflammatory response, obesity is often accompanied by a state of systemic inflammation, characterized by increased levels of pro‐inflammatory cytokines such as TNF‐α, IL‐6, and IFN‐γ, alongside a decrease in anti‐inflammatory cytokines such as IL‐4 and IL‐10." (PMID 39968210, 2025). "Obesity also creates a state of chronic low-grade inflammation-excess adipose tissue secretes pro-inflammatory cytokines (e.g., IL-6, TNF-α) and alters adipokine profiles (leptin up, adiponectin down), fostering a microenvironment conducive to neoplastic growth." (PMID 41041441, 2025). "In obesity, the accumulation of lipids in the adipose tissue triggers an inflammatory response which includes the secretion of proinflammatory cytokines such as Tumor necrosis factor-alpha (TNF‐α)." (PMID 38727993, 2025). "Leptin is involved in the upregulation of IL-6 and TNF-α, contributing to obesity-related low-grade inflammation, promoting vascular dysfunction by contributing to hypertension, angiogenesis, and atherosclerosis, and interacting with insulin, affecting glucose and lipid metabolism." (PMID 40724644, 2025). "TNF-α: Tumor necrosis factor-alpha is an important cytokine used to assess systemic inflammation that regulates multiple pro-inflammatory responses, increases oxidative stress, and takes part in chronic inflammation, obesity, and insulin resistance processes." (PMID 41154646, 2025). "Furthermore, obesity is linked to elevated levels of inflammatory mediators, including C-reactive protein (CRP), tumor necrosis factor-α (TNF-α), and interleukin-6 (IL-6)." (PMID 41163684, 2025). "Pro-inflammatory cytokines (IL-1β, IL-6, TNF) surge while IL-10 drops in obesity." (PMID 41562075, 2025). "Furthermore, obesity triggers chronic low‐grade inflammation, with adipose tissue producing pro‐inflammatory mediators such as TNF‐α and IL‐6." (PMID 40661797, 2025). "Importantly, our data show that RAGE KO mice exhibited significantly lower plasma levels of TNF-α, a key pro-inflammatory cytokine elevated in obesity." (PMID 40863143, 2025). "Moreover, the elevated levels of TNFR1 in obesity are a response to the increased production of TNF-α in hypertrophied visceral fat." (PMID 40153192, 2025). "Obesity has been related to the chronic activation of proinflammatory signaling pathways, in which the NFκB is a critical component that controls the transcription and release of downstream pro‐inflammatory cytokines, such as IL‐6, TNF‐α, and IL‐1β." (PMID 39968210, 2025). "In obesity, adipose tissue becomes metabolically dysregulated and secretes elevated levels of pro-inflammatory cytokines, such as tumor necrosis factor-alpha (TNF-α) and interleukin-6 (IL-6), along with altered levels of adipokines including leptin and adiponectin." (PMID 40690028, 2025). "Moreover, obesity is related to elevated levels of circulating pro‐inflammatory markers, such as TNF‐α and IL‐6." (PMID 40620232, 2025). "This review examines macrophage ontogeny, polarization, and functional heterogeneity in ORBC, highlighting how obesity-induced cytokines (e.g. TNF-α, IL-6), reactive oxygen species, and metabolic reprogramming collectively reshape the TME to foster tumor initiation, progression, and metastasis." (PMID 41310829, 2025). "However, in obesity, there is an increase in the secretion of pro-inflammatory cytokines, such as TNFα, IL-6, and Monocyte Chemoattractant Protein-1 (MCP-1), while the secretion of anti-inflammatory adipokines like adiponectin is reduced." (PMID 41226298, 2025). "Additionally, semaglutide demonstrated neuroprotective benefits to the CNS leading to enhancement to cell survival, decreased M1-like microglia numbers, and reduced interleukin-6 and TNF-α levels in different brain areas in obesity." (PMID 40240584, 2025).